PBK (PDZ binding kinase)
Diseases named in the same sentence as PBK in open-access papers (continued):
Sharing a sentence is not in itself a finding about the gene and the disease.
cancer (123 papers, 2008 to 2026). A tumor composed of atypical neoplastic, often pleomorphic cells that invade other tissues. "Each unit increase in genes DIAPH3, and PBK expression is associated with a 1.6-fold higher hazard of death, suggesting its potential role in cancer progression." (PMID 38914609, 2024). "Combined with the PBK Western blotting results, the study confirms the close association between high PBK expression and cancer cell survival and proliferation, thereby enhancing the accuracy of the findings." (PMID 39628686, 2024). "The PBK gene, which was also overexpressed, was found to have an association with the poor survival of patients in different cancer, and this made PBK a suitable prognostic biomarker and a potential therapeutic target." (PMID 36980449, 2023). "In summary, the common PBK mutation types in most cancers are nonsense substitution, missense substitution, and synonymous substitution." (PMID 34859049, 2021). "Many studies have indicated that high PBK expression is associated with a more aggressive phenotype in various cancers, including gastric, oral, glioma, lung, colon, colorectal, breast, prostate, and pancreatic cancers." (PMID 30778048, 2019). "The most significant outcome of our studies is a very strong correlation of PBK/TOPK nuclear localization with cancer grade and stage and particularly its association with distant metastases at various sites." (PMID 25909225, 2015). "PBK upregulation exhibits diagnostic and prognostic relevance in cancers." (PMID 39297018, 2024). "Upregulation of PBK/TOPK has also been proven to be associated with cancer diagnosis and prognosis, and, thus, it may be a potential therapeutic target in various malignant tumors." (PMID 33670114, 2021). "PBK gene mutations were unrelated to survival and prognosis of cancers in TCGA." (PMID 34859058, 2021). "Previous studies including our group have highlighted that PBK was required for malignant phenotypes and was associated with poor prognosis of human common cancers, including NPC, oral cancer, breast cancer, colorectal cancer, leukemia and lymphoma, ovarian cancer, lung cancer, and glioma." (PMID 33431797, 2021). "The upregulation of PBK has diagnostic and prognostic significance in cancer." (PMID 34859058, 2021). "Finally, we examined the association between PBK methylation and OS in 22 cancer types and found that in LGG, THCA, GBM, and PCPG, a higher methylation level was associated with a lower risk of death, whereas a positive association was observed between PBK methylation and mortality in UCEC." (PMID 34859058, 2021). "Moreover, high PBK expression was associated with a poor prognosis in many cancers." (PMID 30778048, 2019). "The high expression level (EL) of PBK correlates closely with phenomena such as cell proliferation, metastasis, and drug resistance, making it an imperative therapeutic target in cancer." (PMID 39628686, 2024). "In our pan-cancer analysis, PBK was significantly upregulated, particularly in LUAD patients, and displayed poor prognosis." (PMID 37993518, 2023). "We used TIMER2.0 and CGGA for a comprehensive and systematic CDK1/PBK/CHEK1 oncogenic signature analysis for their differential expression in pan cancers and their correlation in GBM." (PMID 38003585, 2023). "PBK, a serine/threonine kinase belonging to the mitogen‐activated protein kinase kinase (MAPKK) family, is often overexpressed in cancers and is associated with poor prognosis." (PMID 37341142, 2023). "PBK/TOPK protein is difficult to detect in normal tissues but has been found in a variety of malignant tumors." (PMID 36171591, 2022). "It was reported that the overexpression of PBK/TOPK protein usually indicates a poor prognosis for malignant tumors." (PMID 36171591, 2022). "Considering its oncogenic roles, PBK/TOPK has been studied as a promising therapeutic target in cancer." (PMID 35203508, 2022).
cancer (continued). "In this study, we first explored the correlation of PBK/TOPK mRNA expression with 33 cancers in TCGA using the Kaplan–Meier survival analysis." (PMID 34603451, 2021). "We further analyzed the correlation between PBK/TOPK expression and the expression of DNA mismatch repair genes and methyltransferase in pan-cancer." (PMID 34603451, 2021). "Given the pivotal roles of T-cell subsets in cancer initiation, progression, and immunotherapy, we focus on how PBK modulates the infiltration of T-cell subsets." (PMID 33431797, 2021). "We also found that PBK was significantly upregulated in cancer samples compared to their paired normal samples (p < 0.01), consistent with the results from TCGA, except for DLBC and TGCT." (PMID 34859049, 2021). "We analyzed the differential expression of PBK in 33 cancers as compared to normal tissue using TCGA and GTEx databases." (PMID 34859058, 2021). "In this study, PBK expression was found closely related to immune infiltration cells in various cancers, especially in KIRC, LGG, and LIHC." (PMID 34603451, 2021). "According to the data analyzed from the TIMER2.0, we redrew the heatmap to help readers more intuitively understand the correlation between PBK/TOPK and immune infiltration cells in pan-cancer datasets." (PMID 34603451, 2021). "Considering that chemotherapy and targeted therapy is the common way in cancer therapy and previous study indicated that PBK might promote chemotherapy resistance, we tried to assess the association between PBK expression and the IC50 level from each GDSC cell line dataset." (PMID 34859049, 2021). "We identified 4 TFs and 3 miRNAs that were related to PBK upregulation and downregulation, respectively, in cancer." (PMID 34859058, 2021). "Several reports have also provided evidence for the anticancer effects of PBK inhibitors on cancer cells." (PMID 35115926, 2021). "Considering that the amount of the normal samples is relatively small in TCGA database, we combined the TCGA database and the GTEx database to analyze the difference of PBK expression levels in 31 cancer types." (PMID 34859049, 2021). "The aim of the present study was to examine the role of PBK in different cancers and elucidate the molecular mechanisms and functions of PBK and its interacting molecules in carcinogenesis." (PMID 34859058, 2021). "PBK/TOPK expression showed different correlations with different immune checkpoint genes in various cancers." (PMID 34603451, 2021). "This study provided novel insight into the functional role of PBK in different types of cancer and also revealed its potential correlation with immune infiltration and chemoresistance." (PMID 34859049, 2021). "It is noteworthy that PBK/TOPK expression was significantly negatively correlated with TMB in THYM which is also in contrast to other cancers." (PMID 34603451, 2021). "Here we analyzed the correlation between PBK expression and immune checkpoint molecules in different cancers." (PMID 34859058, 2021). "In this study, we provided evidence for PBK as a pan-cancer biomarker based on gene expression and survival data and analyses of immune cell infiltration, TFs, miRNAs, pharmacogenomics, and related intracellular signaling pathways." (PMID 34859058, 2021). "We also examined the correlation between PBK methylation and expression in 32 cancer types and found that the expression levels of PBK and its TFs were negatively correlated with PBK methylation, with positive correlations observed only in a few cases." (PMID 34859058, 2021). "We explored the functional enrichment of PBK in cancer by mapping the protein–protein interaction network of PBK with the STRING database." (PMID 34859058, 2021). "In summary, our analysis indicated that PBK was significantly upregulated in various cancers and served as a biomarker in multiple tumor progress and patient survival." (PMID 34859049, 2021).
cancer (continued). "First, we performed paired comparisons of differences in PBK/TOPK mRNA expression levels between cancer and normal tissues from individuals with the same cancer." (PMID 34603451, 2021). "High expression of PBK is significantly associated with poor prognosis and clinicopathologic stages I, II, and III in different cancers." (PMID 34859049, 2021). "The expression of PBK/TOPK increased from pathologic stages I to IV in various cancers including ACC, KICH, KIRC, KIRP, and LUAD." (PMID 34603451, 2021). "We examined the relationship between the expression of PBK and its interaction partners and the activation or inhibition of cancer-related signaling pathways using the GSCALite platform." (PMID 34859058, 2021). "PBK/TOPK is becoming an attractive target in chemotherapeutic drug design because of its important role in cancer progression." (PMID 33670114, 2021). "Images of immunohistochemical staining for PBK in various cancers obtained from the HPA database revealed the low to moderate expression of the PBK protein in many tumors." (PMID 34603451, 2021). "Our results demonstrate that PBK plays an important role in carcinogenesis and is a potential therapeutic target in cancer treatment." (PMID 34859058, 2021). "Our results showed that PBK is positively correlated with TMB in 22 cancer types and is significantly correlated with THYM in TMB." (PMID 34859049, 2021). "PDZ‐binding kinase (PBK) has previously been shown to mediate chemoresistance of cancer cells to anticancer drugs." (PMID 32237067, 2020). "Further studies are required for elucidation of mechanistic role of PBK in autophagy of cancer cells in response to various cellular stresses." (PMID 32237067, 2020). "PDZ‐binding kinase (PBK) is highly expressed in many cancer cells and is known as MAPKK‐like protein kinase." (PMID 32237067, 2020). "The abnormal high expression of PBK in cancers is attributed to the deregulation of several transcription factors, such as E2F, ATF, c-Myc, and FOXM149–51." (PMID 30778048, 2019). "PBK appears to represent an important nexus for various signalling networks that promote cancer proliferation and invasion and thus pbk can exploit other oncogenic triggers to enhance its own expression." (PMID 30237440, 2019). "Markedly, the CTA genes ATAD2, CEP55, FANCA, KIF2C, NUF2, OIP5, and PBK had significantly positive expression correlations with the PLK1 expression in 30 cancer types (Pearson correlation, FDR<0.1)." (PMID 30631355, 2018). "The PBK/TOPK protein is up-regulated in certain types of cancer cells such as breast, colon, lung and glioma cancer cells, but is difficult to be detected in normal tissues except several fetal tissues and germ cells of the testis." (PMID 28388576, 2017). "Due to the specific expression in cancer cells, targeting PBK has been attempted as a potential therapy for HCC." (PMID 28525379, 2017). "The overexpression of PBK in human cancers is attributed to the deregulation of TFs, such as c-Myc, E2F and CREB/ATF." (PMID 28525379, 2017). "Accumulating literatures provide evidence that PBK is deregulated and plays an important role in human cancers." (PMID 28525379, 2017). "TOPK (T-lymphokine-activated killer cell-originated protein kinase, also known as PBK or PDZ-binding kinase) is a Ser/Thr protein kinase that is highly expressed in various types of human cancer." (PMID 26933922, 2016).
cancer (continued). "Since PBK seems to play an important role in the mitotic phase of the cell cycle of some cancer cell types, we also investigated the effect of PBK knockdown on cells arrested in the G2/M phase of the cell cycle." (PMID 26081429, 2015). "We also observed that nuclear PBK localization strongly correlated with Gleason score and cancer stage." (PMID 25909225, 2015). "Our data indicate that geranylgeranylation signaling controls expression of PBK, a gene whose product regulates cell mitosis, thus is important for cancer cell proliferation." (PMID 25745361, 2015). "Amongst these are regulators of mitosis e.g. BUB1, CDC20, and PBK, which are known to play important roles in the ontology of various types of cancers." (PMID 18847459, 2008). "A recent study demonstrated that PBK also plays a role in G1/S transition through phospho-activation of Chk1 and Cdc25C in response to replication stress, and that deletion of PBK renders cancer cells vulnerable to radiation-induced DNA damage." (PMID 38596293, 2024). "However, PBK is considered an oncogenic form of MEK1 and is active in cancer cells while largely unexpressed in normal tissues, which makes PBK more valuable as a promising antitumor target." (PMID 38460944, 2024). "Overall, genes between the high and low PBK expression groups may have a greater role in immune function, and cancer progression in LUAD." (PMID 37993518, 2023). "Dysregulated PBK/TOPK expression promotes cancer growth and progression." (PMID 35203508, 2022). "Beihua Kong and colleagues from Shandong University, Jinan, China, showed how PDZ-binding kinase (PBK), an enzyme that promotes the proliferation and spread of cancer cells, activates a signaling pathway that renders tumors resistant to treatment with olaparib." (PMID 35859118, 2022). "The expression of PBK in pan-cancers was studied by Onconmine and TIMER." (PMID 35065633, 2022). "These conclusions suggest that the possibility of PBK to be a cancer therapeutic target." (PMID 35065633, 2022). "In this study, we revealed the expression of PBK in pan-cancers and HCC." (PMID 35065633, 2022). "In this study, we explored the expression of PBK in pan-cancers using oncomine and TIMER databases." (PMID 35065633, 2022). "Interestingly, even coffee and its active ingredient, caffeic acid (CaA), were demonstrated to reduce the risk of cancers, by suppressing PBK/TOPK activity." (PMID 33670114, 2021). "Additionally, we found that PBK expression was positively correlated with cancer stage in ACC, KICH, KIRC, KIRP, and LUAD." (PMID 34859058, 2021). "Next, we analyzed PBK/TOPK mRNA expression in various cancers from TCGA." (PMID 34603451, 2021). "PBK knockdown was shown to result in cytokinesis defects in cancer cells." (PMID 34859058, 2021). "Moreover, PBK expression is positively relevant to MSI in nine cancer types, most of which also positively correlated with TMB." (PMID 34859049, 2021). "It has been shown to be a critical gene in the regulation of mitosis and tumorigenesis, but the role of PBK in various cancers remains unclear." (PMID 34859049, 2021). "Given the importance of PBK in cancer, we explored TFs and miRNAs that regulate PBK expression." (PMID 34859058, 2021). "Based on this observation combined with the survival data, we speculate that PBK affects the prognosis of cancers—particularly KIRC and LIHC—by enhancing immune cell infiltration." (PMID 34859058, 2021). "Our study demonstrated that PBK may serve as a biomarker to determine the early stages in various cancers." (PMID 34859049, 2021). "Furthermore, PBK expression is strongly associated with TMB in 23 cancer types and associated with MSI in nine cancer types." (PMID 34859049, 2021). "PBK/TOPK is upregulated in a wide range of mitotically active cancers; thus, a series of clinical studies have been conducted to investigate whether the levels of PBK/TOPK mRNA or protein have diagnostic or prognostic value." (PMID 33670114, 2021).
cancer (continued). "Overall, we propose that PBK represents a potential therapeutic target in cancer therapy." (PMID 34603451, 2021). "As such, new PBK inhibitors for cancer treatment are needed." (PMID 34859058, 2021). "We observed a significant correlation between PBK/TOPK expression and TILs in most cancers." (PMID 34603451, 2021). "Thus, PBK is a prognostic biomarker in many cancers, especially in ACC and LUAD as well as in KIRC and KIRP, which has not been previously reported." (PMID 34859058, 2021). "Because the thymus is an immune organ, the role of PBK in THYM may be different from other cancers and it deserves further exploration." (PMID 34603451, 2021). "Also, high PBK expression is involved in the cell cycle and relevant biological functions and signaling pathways in different cancer types." (PMID 34859049, 2021). "In particular, MEIS1, FLT3, TNF, PBK, and IGF2BP, all associated with cancer, were down-regulated." (PMID 32698374, 2020). "However, information about signaling pathways or stimuli involving anticancer drugs that regulate PBK activity or expression to affect cancer cells still lacks." (PMID 32237067, 2020). "Interestingly, PBK expression was predominantly nuclear in PrCa and identified aggressive disease subtype suggesting its potential as a prognostic biomarker for cancer progression." (PMID 30237440, 2019). "Likewise, oncogenic transcription factors such as ETS, c-Myc and E2F, which are all activated in PrCa, have been shown to drive PBK expression in various cancer types." (PMID 30237440, 2019). "PBK is rarely expressed in normal tissues except for fetal and germ cells but is highly trans-activated in various cancers, making it a promising molecular target for cancer screening and targeted therapy." (PMID 30778048, 2019). "PDZ-binding kinase (PBK) promotes the malignant progression of various carcinomas." (PMID 30778048, 2019). "The remaining genes are a part of several pathways involved in cancer etiology such as: Negative regulation of stress activated MAPK cascade (PBK and PINK1), intracellular signal transduction and regulation of autophagosome assembly (LRRK2 and PINK1) and RNA degradation (PABC3 and DDX6)." (PMID 29879995, 2018). "Deregulation of PBK has been reported in other cancer types." (PMID 28525379, 2017). "High PBK/TOPK expression was associated with poor prognosis for cancer relapse, especially in lymph node-negative breast cancer patients." (PMID 27347940, 2016). "PBK is a mitotic serine/threonine protein kinase overexpressed in various actively proliferative normal cells as well as malignant tumor cells; thus, it may be a potential therapeutic target in various malignant tumors." (PMID 36232712, 2022). "Interestingly, PBK is overexpressed in various cancer tissues." (PMID 35154063, 2022). "Subsequently, we explored whether PBK expression is correlated with patient prognosis, and the results showed a negative correlation between PBK expression and patient survival time in most types of cancer." (PMID 34859049, 2021). "Thus, PBK likely plays an important role in cancer development." (PMID 34859058, 2021). "Thus, PBK is a novel autophagy regulator in cancer development." (PMID 30778048, 2019). "However, PBK acts on different substrates in different cancer cells." (PMID 30778048, 2019). "Our functional studies showed that knocking down of PBK expression suppresses cancer cell proliferation and colony formation in NPC cells, as well as HI-TOPK-032 treatment could induce a massive increase in ROS and activate P38/JNK pathways to promote apoptosis." (PMID 27049917, 2016). "However, the signaling that regulates expression of PBK in cancer cells remains elusive." (PMID 25745361, 2015).